GCG (glucagon)
Diseases named in the same sentence as GCG in open-access papers (continued):
Sharing a sentence is not in itself a finding about the gene and the disease.
heart failure (49 papers, 2012 to 2026). Inability of the heart to pump blood at an adequate rate to meet tissue metabolic requirements. "When heart failure was induced in these preparations by means of pentobarbital, glucagon caused a recovery to control levels." (PMID 30482191, 2018). "Moreover, there are glucagon-producing tumors in patients called glucagonomas that have been accompanied by and might have caused heart failure." (PMID 37629010, 2023). "Due to its potential inotropic properties, glucagon has long been evaluated as a potential treatment for symptomatic heart failure with data demonstrating mixed clinical outcomes." (PMID 40593987, 2025). "Acute dapagliflozin treatment also increased plasma glucagon concentrations, lowered the insulin-to-glucagon ratio, and increased whole-body glucose turnover in sham-surgery and heart-failure rats." (PMID 39680452, 2024). "A more recent, larger study (140 heart failure patients and 20 healthy controls) measured a significant elevation in the blood glucagon concentrations in patients suffering from systolic heart failure compared to appropriate control subjects." (PMID 37629010, 2023). "Successful administration of glucagon has been reported in a range of cardiovascular disorders, including heart failure and cardiogenic shock." (PMID 36946315, 2023). "In an early study on heart failure, much higher values than these normal plasma glucagon concentrations of 10–20 pM, namely 260 pg/mL of glucagon, were measured in patients (about 700 pM,)." (PMID 37629010, 2023). "Clinically, glucagon use is accompanied by nausea and vomiting in patients during clinical heart failure trials." (PMID 37629010, 2023). "The gut microbiota and its metabolism were altered during heart failure, which increased blood glucose and glucagon in the host." (PMID 35859583, 2022). "In another study, a continuous infusion of glucagon at an average dose of 4 mg/h over several days was reported to produce distinct improvement in the clinical state of 12 of 16 patients, with heart failure or cardiogenic shock." (PMID 30482191, 2018). "For instance, 24 out of 50 patients who had either heart failure, cardiogenic shock or both showed some clinical improvement after adding glucagon to a combined therapy which included digitalization, furosemide and spironolactone." (PMID 30482191, 2018). "One proposed physiologic explanation for the heart failure finding is the inhibitory effect of this class on glucagon, a positive inotropic hormone." (PMID 29270438, 2017). "Due to some similarities between kidney disease and heart failure, increasing glucagon signaling might also be beneficial in chronic kidney disease patients." (PMID 39548491, 2024). "One might speculate that some of the beneficial effects of scubitiril in heart failure patients might be due to elevated plasma glucagon levels." (PMID 37629010, 2023). "A causal relationship is sometimes made likely when the surgical removal of the glucagon-producing tumor is accompanied by an improvement in or disappearance of an accompanying heart failure, as was reported, for example, by octreotide therapy or surgical removal of the tumor." (PMID 37629010, 2023). "One may speculate that the concentration of glucagon formed in the heart is altered in heart failure (in analogy to, for instance, atrial natriuretic peptide)." (PMID 37629010, 2023). "At least one study on heart failure patients exhibited 700 pM of glucagon." (PMID 37629010, 2023). "Thus, attempts for a therapeutic use of glucagon have been made in resistant cardiac failure, myocardial infarction, hypotension following cardiac operations, intoxication with β-/calcium channel blockers and heart block." (PMID 27568179, 2016). "The pathomechanism of glucagon-induced heart failure remains subject to discussion." (PMID 25520848, 2014). "Moreover, in the past, glucagon has been therapeutically used for heart failure treatment." (PMID 27568179, 2016).
heart failure (continued). "Thus, elevated glucagon levels in the blood may accompany heart failure." (PMID 37629010, 2023). "Noradrenaline derived from the gut microbiota was correlated with glucagon and IGTT-AUC in heart failure." (PMID 35859583, 2022). "Moreover, if patients with heart failure are given levosimendan or milrinone, which are PDE inhibitors, based on the present data, glucagon would be a positive inotropic agent." (PMID 39859412, 2025). "In cardiac failure with a low systolic blood pressure, glucagon was tried not as a single bolus, but as a 5 mg per hour intravenous infusion for several days." (PMID 37629010, 2023). "No patient in the study developed features of heart failure or pulmonary hypertension further adding to the efficacy of glucagon in maintaining stable glycaemia without excessive volume intake." (PMID 33013678, 2020). "In our study, glucagon did not exert inotropic effects on any of the human tissues studied, whether they were obtained from explanted hearts of patients with advanced heart failure or from donors without heart failure." (PMID 37254135, 2023). "The glucagon inotropic action in human heart is well represented in not failing heart, but progressively declines in the failing heart, becoming undetectable in severe heart failure condition." (PMID 27568179, 2016). "The effects of long-time stimulation of glucagon on the myocardium have not been studied yet; however, sarcoplasmic reticulum calcium leak can be discussed as a possible mechanism for glucagon-induced heart failure." (PMID 25520848, 2014). "Indeed, although positive results have been reported in some cases, glucagon is considered devoid of beneficial clinical effects in patients with congestive heart failure, and its administration is not recommended in current heart failure therapeutics guidelines." (PMID 30482191, 2018). "The reduced risk of hospitalization for heart failure with empagliflozin, which is present in patients with and without baseline heart failure, might be partly explained by a direct enhancement of myocardial function, determined by the increased levels of glucagon, and by its natriuretic effect." (PMID 27568179, 2016).
Impaired glucose tolerance (38 papers, 2010 to 2026). An abnormal resistance to glucose, i.e., a reduction in the ability to maintain glucose levels in the blood stream within normal limits following oral or intravenous administration of glucose. "It is of interest that increased glucagon levels upon oral glucose challenge can also be found in healthy individuals and has even been associated with a lower risk for impaired glucose tolerance (IGT)." (PMID 36686477, 2022). "Specific deletion of the glucagon gene in the α-cell in adult mice led to impaired glucose tolerance, reduced β-cell mass and function, islet inflammation, β-cell endoplasmic reticulum stress, and altered β-cell ultrastructure." (PMID 42134544, 2026). "These individuals were leaner, had a higher insulin sensitivity, a lower risk for impaired glucose tolerance (IGT) (OR 0,44-0,53 in all cohorts, p<=0.009) and lower fasting glucagon levels." (PMID 36686477, 2022). "In NAFLD, glucagon resistance has been proposed to drive impaired glucose tolerance and T2D in a subset of patients." (PMID 35718339, 2022). "Animal studies have reported that total gastrectomy resulted in impaired glucose tolerance, possibly due to delayed insulin and increased glucagon release." (PMID 31292518, 2019). "We previously demonstrated that the ability of Xen to amplify the effects of GIP on insulin and glucagon release is greatest in humans with impaired glucose tolerance and therefore, only subjects with impaired glucose tolerance were studied." (PMID 29466430, 2018). "In addition, it was found that early glucagon inhibition is impaired in those with impaired glucose tolerance." (PMID 36422091, 2022). "Furthermore, elevated glucagon secretion is manifest long before the onset of impaired glucose tolerance." (PMID 29242971, 2019). "High glucagon levels are also apparent in prediabetic patients, who exhibit impaired glucose tolerance, suggesting that impaired glucagon suppression may contribute to the development of T2DM." (PMID 29740399, 2018). "The pathophysiology of impaired glucose tolerance on the other hand has been shown to be characterized by heightened peripheral insulin resistance, normal hepatic insulin sensitivity, progressive ß-cell dysfunction, reduced secretion of the insulin-tropic hormones, and deranged glucagon secretion." (PMID 41296757, 2025). "While glucagon non-suppression in the postprandial state was long thought to be a hallmark of impaired glucose tolerance, based on smaller studies, this did not hold true in our large meta-analysis, where post-load non-suppression of glucagon was detected in those with a healthier phenotype." (PMID 35872982, 2022). "Thus, Nuf mice with a gain-of-function CaSR mutation exhibited impaired glucose tolerance, which was associated with reduced pancreatic islet mass and hypoinsulinemia as well as a lack of glucose-mediated suppression of glucagon secretion." (PMID 28575322, 2017). "After 12 weeks of Eriomin supplementation with 200, 400, or 800 mg per day, there was a significant decrease in fasting glycemia, impaired glucose tolerance, HOMA‐IR, HbA1c, glucagon, C‐peptide, hsCRP, IL‐6, and TNF‐α." (PMID 31183921, 2019). "We previously provided genetic evidence for a role for insulin by demonstrating that alpha cell-specific insulin receptor knockout (alphaIRKO) mice exhibit hyperglucagonemia, impaired glucose tolerance, and a lack of suppression of glucagon release in response to insulin stimulation." (PMID 33839150, 2021). "However, T2D and impaired glucose tolerance are characterized by impaired postprandial suppression of glucagon and could potentially benefit from non-pharmacological reductions in glucagon." (PMID 28744255, 2017). "In adults with impaired fasting glucose (IFG) with or without impaired glucose tolerance (IGT), higher plasma glucose concentrations were necessary to suppress glucagon secretion compared to individuals with normal glucose metabolism (NGM)." (PMID 39027470, 2024).
prediabetes (32 papers, 2017 to 2026). "Others suggest that HbA1c-defined prediabetes is associated with a defective insulin response in combination with inappropriate suppression of glucagon." (PMID 38397965, 2024). "This highlights a gap in the literature regarding glucagon fluctuations after fat- and protein-rich meals in individuals with T2DΜ and prediabetes." (PMID 41575482, 2026). "Normally, during nutrient intake, insulin secretion is increased and glucagon secretion is repressed, but when plasma glucose concentration increases, a state of prediabetes occurs." (PMID 34829598, 2021). "Given the role of excess hepatic glucose production and reduced glucose clearance in the pathophysiology of prediabetes the inhibition of glucagon by GABA, in addition to β-cell replication, could favorably improve the insulin/glucagon ratio." (PMID 39619323, 2024). "However, dysregulation of α‐cell function in prediabetes occurs early and independently of changes in β‐cells, which suggests insulin having a less significant role on glucagon control." (PMID 35822422, 2022). "In a mouse model of prediabetes, empagliflozin treatment improved LV contractility and cardiac microcirculation in combination with an increase in plasma ketone bodies, glucagon concentration, and glucagon/insulin ratio." (PMID 35409011, 2022). "Furthermore, in this subject, glucose showed prediabetes, as indicated by glucose, C-peptide and glucagon responses, and the Matsuda index." (PMID 29225708, 2017). "The altered glucagon regulation may be caused by insulin resistant alpha cells or by the overall higher protein/food intake in the HFD-fed animals and may over time lead to poor glycemic control and prediabetes as observed in humans." (PMID 38427692, 2024). "Therefore, higher insulin action in pediatric IFG, compared to other forms of prediabetes, may additionally explain the relatively lower glucagon levels placing them in the range of NG-O." (PMID 39027470, 2024). "The lack of early glucagon suppression, especially within the first 30-60 minutes, may be an early and reliable hallmark of prediabetes and IGT in adults, although contradictory results question this." (PMID 36686477, 2022). "Incorporation of 20 g of almonds, 30 min before each major meal led to a significant decrease in PPHG (as revealed in OGTT-based study phase) and also improved insulin, C-peptide, glucagon levels, and improved glucose variability and glycemic parameters on CGMS in participants with prediabetes." (PMID 36732571, 2023). "Deteriorating glycemic control over time was associated with insufficient glucagon-suppression during OGTT and an early lack of glucagon suppression exists in prediabetes." (PMID 36686477, 2022). "In particular, the impact of high-fat diet (HFD) feeding—widely regarded as a model of prediabetes —on glucagon secretion is not well characterised." (PMID 32446876, 2020).
Hypertension (30 papers, 2008 to 2026). The presence of chronic increased pressure in the systemic arterial system. "Based on these findings, glucagon has been used clinically as an emergency treatment for hypertension caused by β-blocker or calcium channel blocker overdose." (PMID 40822953, 2025). "The increased levels of glucagon and adrenaline could cause tachycardia or hypertension." (PMID 25520819, 2014). "In hypertension-induced cardiac hypertrophy in rats, the efficacy of glucagon in raising the left ventricular pressure was less than that in control rat hearts, whereas the positive chronotropic effects of glucagon remained unaltered." (PMID 37629010, 2023). "The model was adjusted for age, TC, TG, HDL, LDL, FPG, HbA1c, glucagon, C-peptide, insulin, Vit D, current smoking, and hypertension." (PMID 37102159, 2023). "We recommend that surgical intensive care units using labetalol infusions to control refractory hypertension have glucagon, epinephrine, insulin, phosphodiesterase inhibitors, and vasopressin readily available for administration." (PMID 18505576, 2008). "Pain can have several effects on the body’s homeostasis, including the release of catecholamines, leading to cardiovascular and circulatory stress manifested in tachycardia and hypertension, and the release of cortisol, which increases glucagon levels and decreases insulin levels." (PMID 37760305, 2023). "However, positive inotropic effects of glucagon can precipitate severe hypertension." (PMID 36008817, 2022).
Alzheimer disease (27 papers, 2014 to 2026). A progressive, neurodegenerative disease characterized by loss of function and death of nerve cells in several areas of the brain leading to loss of cognitive function such as memory and language. "In contrast, mitochondrial genes associated with Alzheimer’s disease, oxidative phosphorylation and Parkinson’s disease were more abundant in the A3 cluster (OB mice), suggesting an adaptive lowering of glucagon secretion in OB mouse alpha cells through increased oxidative phosphorylation." (PMID 39508880, 2025). "KEGG pathway analysis for these genes identified several key signaling pathways, including the insulin signaling pathway, Parkinson's disease, non-alcoholic fatty liver disease (NAFLD), glucagon signaling pathway, and Alzheimer's disease." (PMID 32194838, 2020). "NEP inactivates a wide range of peptide substrates including enkephalins, neurokinin A, substance P, bradykinin, endothelins, somatostatin, adrenomedullin, bombesin‐like peptides, glucagon, thymopentin as well as the amyloid‐β (Aβ) which accumulates in Alzheimer's disease (AD)." (PMID 35212467, 2022). "While considerably less is known about the CNS effects of GIP compared to GLP-1 and glucagon, dual GIP/GLP-1 RA treatment has shown positive effects on animal models of Alzheimer’s disease and Parkinson’s disease (Hölscher, 2018)." (PMID 31133864, 2019). "Interestingly, several disease-related pathways were significantly enriched, including those associated with neurodegeneration (e.g., Parkinson’s, Huntington’s, and Alzheimer’s diseases), diabetes neuropathy, and immune-related signaling, such as the HIF-1 and glucagon signaling pathways." (PMID 40725077, 2025).
non-alcoholic fatty liver disease (26 papers, 2018 to 2026). "Nonalcoholic fatty liver disease has been proposed to impair hepatic sensitivity to glucagon signaling, causing higher levels of fasting amino acid and glucagon levels." (PMID 34382579, 2021). "Additionally, hepatic cholesterol levels impact glucagon sensitivity, relevant to the development of non-alcoholic fatty liver disease, which is linked to both increased liver cholesterol and glucagon resistance." (PMID 39125351, 2024). "This could be relevant to the pathogenesis of non-alcoholic fatty liver disease, which is associated with both hepatic cholesterol accumulation and glucagon resistance." (PMID 35718339, 2022). "Hepatic glucagon action has been associated with elevated fatty acid oxidation and might act protectively against non-alcoholic fatty liver disease (NAFLD)." (PMID 33143653, 2020). "Alanine and glutamate both stimulate glucagon secretion, and alanine in particular is dysregulated in nonalcoholic fatty liver disease." (PMID 32867058, 2020). "Similarly, nonalcoholic fatty liver disease (NAFLD) has a high fasting plasma glucagon concentration due to reduced hepatic glucagon sensitivity as suggested by rodent studies." (PMID 40069760, 2025). "Hepatic steatosis might be causally involved in the impairment of the liver–alpha cell axis as individuals with non-alcoholic fatty liver disease (NAFLD) display elevated fasting glucagon and higher plasma levels of the sum of l-amino acids compared with individuals without the disease." (PMID 33275161, 2021).